APEX1 (apurinic/apyrimidinic endodeoxyribonuclease 1)
Diseases named in the same sentence as APEX1 in open-access papers (continued):
Sharing a sentence is not in itself a finding about the gene and the disease.
colon cancer (18 papers, 2008 to 2025). "We indicated that the APEX1 Asp148Glu genotype has a specifically association with colon cancer risk." (PMID 18823566, 2008). "Furthermore, APEX1 expression was associated with Jagged1 in tissues from colon cancer patients." (PMID 41294868, 2025). "APEX1 overexpression in human colon cancer cell lines induces cell proliferation, anchorage-independent growth, migration, invasion, and angiogenesis both in vitro and in vivo." (PMID 41294868, 2025). "CD133+/ESA+ colon cancer stem cells present significantly higher APEX1 mRNA expression than corresponding colon cancer cells." (PMID 37283798, 2023). "APEX1-induced JAG1 expression in colon cancer cells, which subsequently activated Notch signaling to promote tumorigenicity, migration, invasion, angiogenesis, tumor formation, and metastasis in mouse xenograft models." (PMID 25309874, 2014). "APEX1 can activate Notch signal pathway via Jagged1 in colon cancer." (PMID 37283798, 2023). "Considering that APEX1 could drive colon cancer progression via upregulating Jagged1 26, we speculated that APEX1 might modulate CD133+ GBC-SD cell biological function by regulating Jagged1." (PMID 37283798, 2023). "Moreover, a previous study has confirmed that APEX1 can facilitate colon cancer oncogenesis by regulating Jagged1 expression." (PMID 37283798, 2023). "The adjusted ORs for the APEX1 Asp/Glu and Glu/Glu genotypes compared with Asp/Asp genotype were statistically significant for colon cancer, but not for rectal cancer (OR 3.04, 95%CI 1.38–6.71, p = 0.006 for colon cancer; OR 1.61, 95%CI 0.64–4.09, p = 0.315 for rectal cancer)." (PMID 18823566, 2008). "More specifically, the APEX1 signaling pathway plays a crucial role in regulating colon CSC growth, whereas FEN1, FANCG and RAD23B were up-regulated in chemo-resistant human colon cancer cell lines." (PMID 35805102, 2022). "Apurinic-apyrimidinic endonuclease-1 (APEX1), a multiple-functional DNA repair enzyme, promotes colon cancer progression through activating the JAG1/Notch signaling pathway." (PMID 25309874, 2014).
ovarian carcinoma (18 papers, 2010 to 2024). A malignant neoplasm originating from the surface ovarian epithelium. "Moreover, the expression of APEX1 in PARPi‐resistant ovarian cancer cells was much higher than that in primary ovarian cancer cells." (PMID 38973255, 2024). "Overall, these data indicate that APEX1 is essential for the LLPS of KAT6A and the interaction of KAT6A with PARP1 in PARPi‐resistant ovarian cancer cells." (PMID 38973255, 2024). "Moreover, the interaction between APEX1 and KAT6A or PARP1 was enhanced in PARPi‐resistant ovarian cancer cells during olaparib + cisplatin treatment, indicating the formation of a more stable complex containing KAT6A, PARP1, and APEX1." (PMID 38973255, 2024). "Taken together, these results indicate that APEX1 impairs PARP1 trapping by enhancing KAT6A LLPS, and that the interaction between KAT6A and PARP1 is independent of its transcriptional regulatory function in ovarian cancer." (PMID 38973255, 2024).
lung adenocarcinoma (12 papers, 2013 to 2025). A carcinoma that arises from the lung and is characterized by the presence of malignant glandular epithelial cells. "Of the 16 distinguishing proteins, 8 were significantly elevated in lung adenocarcinoma (COPG1, STOML2, HYOU1, PDIA4, EPRS, APEX1, LRPPRC and NANS) whereas 8 proteins were significantly decreased in lung adenocarcinoma (SPTB, SPTA1, ANK1, SLC4A1, HBG1 and HBG2)." (PMID 27799870, 2016).
liver cancer (11 papers, 2013 to 2023). An epithelial or non-epithelial malignant neoplasm that arises from the liver. "In addition, the establishment of the orthotopic liver cancer model revealed that APEX1 knockdown suppressed numbers of tumor nodules." (PMID 36205565, 2022). "Although the molecular basis of changing the subcellular localization is not clear, the cytoplasmic distribution of APEX1 has been reported to be associated with aggressiveness in some cancers including lung, ovarian, thyroid, breast, and liver cancers." (PMID 31375000, 2019). "IN HPA database, immunohistochemistry showed that the expressions of APEX1, ME1, S100A10 and ACACA in liver cancer tissues were significantly higher than those in paired normal liver tissues, while ADH1C, and CYP2C9 were expressed at low levels in tumor tissues compared with adjacent normal tissues." (PMID 36456877, 2022).
lymph node metastasis (9 papers, 2011 to 2025). "The positive expression of APEX1 was significantly associated with lager tumor size (˃3cm), lymph node metastasis, locoregional invasion, advanced TNM stages (III + IV), and only received biopsy (all P < 0.05) in GBC." (PMID 37283798, 2023). "Moreover, higher serum APEX1 level was associated with lymph node metastasis and shorter survival time of the patients, so serum APEX1 level might also be a potential biomarker for poor prognosis of CCA." (PMID 31454981, 2019). "High serum APEX1 level was correlated with lymph node metastasis and shorter mean survival time, but not with other parameters." (PMID 31454981, 2019). "Because serum APEX1 level was significantly higher in CCA patients with lymph node metastasis than in the patients without metastasis, we further analyzed the correlation between serum APEX1 level and the clinicopathological features of CCA patients." (PMID 31454981, 2019).
leukemia (8 papers, 2015 to 2025). A malignant (clonal) hematologic disorder, involving hematopoietic stem cells and characterized by the presence of primitive or atypical myeloid or lymphoid cells in the bone marrow and the blood. "However, it was noticed that XRCC1 polymorphisms play an important role in the development of ALL, and postnatal exposure to x-rays can modulate leukaemia risk in the presence of APEX1, MLH1, and XRCC4 gene variants." (PMID 26045716, 2015).
multiple myeloma (8 papers, 2013 to 2023). "An interesting new development is the finding that the BER-associated apurinic/apyrimidinic (AP) nucleases, APEX1 and APEX2, contribute in important ways to the regulation of HR in myeloma." (PMID 31139207, 2019). "Genetic and pharmacological inhibition of APEX1 and APEX2 inhibited HR activity in myeloma cells, using a mechanism that involved the ability of AP nucleases to regulate the expression of RAD51 recombinase." (PMID 31139207, 2019).
Stroke (8 papers, 2017 to 2025). Sudden impairment of blood flow to a part of the brain due to occlusion or rupture of an artery to the brain. "Emerging evidence from human genetics, specimens and animal models indicates a significant role of APEX1 in a panel of cardiovascular diseases, including hypertension, restenosis, atherosclerosis, coronary artery disease, and stroke." (PMID 40243693, 2025). "Evidence from human genetics and animal models supports the role of APEX1 in stroke." (PMID 40243693, 2025). "Taken together, APEX1 may possess cell type-specific roles in post-stroke recovery, i.e., barrier-disruptive in the endothelium and pro-survival in neurons, which warrant further studies using tissue-specific APEX1 KO." (PMID 40243693, 2025). "In a rat model of diabetic stroke, E3330, a small-molecule inhibitor of APEX1 redox activity, improves the recovery of neurological functions and the integrity of the blood–brain barrier (BBB), suggesting a possible role of endothelial APEX1 in post-stroke recovery." (PMID 40243693, 2025). "In fact, there is good evidence that supports the regulatory role of non-endothelial APEX1 in stroke." (PMID 40243693, 2025).
triple-negative breast carcinoma (7 papers, 2018 to 2025). An invasive breast carcinoma which is negative for expression of estrogen receptor (ER), progesterone receptor (PR), and human epidermal growth factor receptor 2 (HER2). "APEX1 in module 2 was found affecting cancer RNA metabolism and triple-negative breast cancer." (PMID 30158870, 2018).
atherosclerosis (6 papers, 2017 to 2025). A disease characterized by the build-up of fatty material and calcium deposition in the arterial wall resulting in partial or complete occlusion of the arterial lumen. "Various pathogenic factors associated with hypertension and atherosclerosis can modulate the expression and/or activity of APEX1 in human vascular ECs, including ROS, shear stress, TNF-α, LPS, hypoxia, and oxidized low-density lipoprotein (ox-LDL)." (PMID 40243693, 2025). "Third, although evidence supports the importance of the N-terminal redox function of APEX1 in ECs and atherosclerosis, does the C-terminal endonuclease activity, i.e., DNA repair capacity, of APEX1 play a role in atherosclerosis?" (PMID 40243693, 2025). "Evidence suggests that APEX1 in blood ECs exerts its regulatory influence on the progression of hypertension and atherosclerosis." (PMID 40243693, 2025). "This line of evidence implicates the role of APEX1 in the maintenance of endothelial integrity to quench intimal hyperplasia, an early event of atherosclerosis." (PMID 40243693, 2025). "Emerging genetic and experimental evidence points towards the functional roles of APEX1 in the pathophysiology of cardiovascular diseases, including neointimal formation and atherosclerosis." (PMID 40243693, 2025). "As both intimal hyperplasia and vascular calcification are important pathogenic features of atherosclerosis, current evidence suggests a functional role of SMC APEX1 during atherogenesis." (PMID 40243693, 2025). "However, several critical points need to be addressed to achieve a better understanding of endothelial APEX1 in atherosclerosis." (PMID 40243693, 2025).
cholangiocarcinoma (6 papers, 2019 to 2023). A carcinoma that arises from the intrahepatic biliary tree (intrahepatic cholangiocarcinoma) or from the junction, or adjacent to the junction, of the right and left hepatic ducts (hilar cholangiocarcinoma). "Recently, APEX1 is recognized as a potential diagnostic biomarker in various cancers, such as renal carcinoma, hepatobiliary carcinomas, cholangiocarcinoma, non‐small‐cell lung cancer, etc.8–10,32." (PMID 33875645, 2021). "APEX1 knockdown in cholangiocarcinoma cells is able to down-regulate Jagged1 expression." (PMID 37283798, 2023). "A recent report shows that serum APEX1 can be used as a biomarker for cholangiocarcinomas." (PMID 32167932, 2020). "However, the signaling pathway of APEX1 in cholangiocarcinoma (CCA) has never been reported." (PMID 33946672, 2021).
Hypertension (6 papers, 2017 to 2025). The presence of chronic increased pressure in the systemic arterial system. "It has been reported that increased plasma levels of APEX1, CD55, PSME2, and SERPINC1 are significantly associated with hypertension, and increased plasma levels of APEX1, CD55, GGCT, KRT17, PSME2, and SERPINC1 are associated with diabetes." (PMID 41156831, 2025). "The APEX1 polymorphism has been associated with essential hypertension." (PMID 40243693, 2025). "Augmenting APEX1 expression or activity may contribute to alleviating the pathogenesis of hypertension." (PMID 40243693, 2025).
diabetes (5 papers, 2010 to 2025). "Interestingly, the SLC2A1 TT and APEX1 TT genotypes are risk alleles associated with the clinical outcome of several diseases, including diabetes and other malignancies." (PMID 20540786, 2010).
esophageal cancer (5 papers, 2018 to 2025). A primary or metastatic malignant neoplasm involving the esophagus. "At a FDR of 1%, APEX1 associated with dHRICA in pan-cancer, and at a FDR of 2% it associated with dHRVAE2 in pan-cancer and with APOBECVAE2 in stomach/esophagus cancer." (PMID 35764656, 2022). "We show that transgenic as well as chemical suppression of AP nucleases inhibits RAD51 expression in MM as well as esophageal cancer (not shown) cells, whereas transgenic upregulation of APEX1 as well as APEX2 induces RAD51 expression." (PMID 30301882, 2018).
lymphoma (5 papers, 2019 to 2023). A malignant (clonal) proliferation of B- lymphocytes or T- lymphocytes which involves the lymph nodes, bone marrow and/or extranodal sites. "Interestingly, RNA-seq data from CAG-A3B lymphomas indicate positive associations between APOBEC mutation signature enrichment scores and mRNA levels for Ung2, AP endonuclease 1 (Apex1), and X-ray repair cross-complementing protein 1 (Xrcc1) but not for Rev1." (PMID 37797615, 2023). "An analysis of the mRNA levels of uracil excision repair factors in CAG-A3B lymphomas indicates positive associations between APOBEC signature enrichment and uracil DNA glycosylase 2 (Ung2), AP endonuclease 1 (Apex1), and X-ray repair cross-complementing protein 1 (Xrcc1), but not with Rev1." (PMID 36865194, 2023). "Conversely, WT lymphomas lack an association between these transcripts and APOBEC enrichment score and, in the case of Apex1, may even exhibit a negative association." (PMID 36865194, 2023). "Conversely, lymphomas from WT animals lack an association between APOBEC enrichment scores and these transcripts and, in the case of Apex1, may exhibit a negative association." (PMID 37797615, 2023).
viral infection (5 papers, 2019 to 2025). "Relationships between APEX1 and viral infection have been documented: inhibition of APEX1 redox activity affects Kaposi’s sarcoma-associated herpes virus and its knock down inhibits HIV1 and HIV2/SIV infection." (PMID 33075093, 2020).
Alzheimer disease (4 papers, 2013 to 2022). A progressive, neurodegenerative disease characterized by loss of function and death of nerve cells in several areas of the brain leading to loss of cognitive function such as memory and language. "There is increasing evidence that APEX1 is widely involved in various diseases caused by oxidative stress, such as Parkinson’s disease, ischemic stroke, Alzheimer’s disease, and cancer." (PMID 35311089, 2022). "It is now known that the APEX1/Nrf2/Keap1 is involved in a variety of human diseases and plays a significant role in Alzheimer’s disease and cancer." (PMID 35311089, 2022).
Cognitive impairment (4 papers, 2015 to 2026). Abnormal cognition is characterized by deficits in thinking, reasoning, or remembering. "Here we show that conditional knockout (cKO) of Apex1 in forebrain neurons causes early and progressive cognitive impairment in mice." (PMID 42098305, 2026).
esophageal adenocarcinoma (4 papers, 2016 to 2023). A malignant tumor with glandular differentiation arising predominantly from Barrett mucosa in the lower third of the esophagus. "APEX1 redox function was required for GSK-3β-mediated APEX1 regulation of Nrf2 in Barrett’s related esophageal adenocarcinoma cells." (PMID 35311089, 2022).
myocardial infarction (4 papers, 2017 to 2025). Gross necrosis of the myocardium, as a result of interruption of the blood supply to the area, as in coronary thrombosis. "Although the association of APEX1 exon 5 polymorphisms with myocardial infarction requires validation with a much larger cohort, this line of human genetic evidence suggests a role of APEX1 BER activity in the susceptibility to myocardial infarction." (PMID 40243693, 2025). "Polymorphism of human APEX1 exon 5 148 Asp(A)/Glu(G) has been reported in patients with myocardial infarction." (PMID 40243693, 2025). "APEX1 also has a considerable role in myocardial infarction." (PMID 40243693, 2025).
neuroblastoma (4 papers, 2019 to 2023). Neuroblastoma (NB) is the most common solid, extracranial childhood tumor. "Here, we conducted a three-center case-control study to evaluate the association between APEX1 polymorphisms (rs1130409 T>G, rs1760944 T>G, and rs3136817 T>C) and neuroblastoma risk in Chinese children, consisting of 469 cases and 998 controls." (PMID 31341530, 2019). "In conclusion, our present data suggest that APEX1 polymorphisms affect neuroblastoma susceptibility in a low-penetrance manner." (PMID 31341530, 2019). "We further assessed the combined effect of protective polymorphisms of APEX1 gene on neuroblastoma risk." (PMID 31341530, 2019). "With an aim to investigate the effect of APEX1 gene polymorphisms on neuroblastoma risk, we performed this current three-center case-control study in Chinese population." (PMID 31341530, 2019). "Herein, we for the first time investigated the association between the APEX1 gene SNPs and neuroblastoma risk." (PMID 31341530, 2019). "Furthermore, functional validation should be performed to clarify the underlying mechanisms by which APEX1 gene polymorphisms affect neuroblastoma susceptibility." (PMID 31341530, 2019). "In summary, our data indicate that APEX1 gene polymorphisms may have a weak effect on neuroblastoma susceptibility." (PMID 31341530, 2019). "Subjects carrying 1-3 combined protective genotypes of APEX1 have a lower risk of neuroblastoma when compared with those without a protective genotype, though not statistically significant (adjusted OR = 0.81, 95%CI = 0.64‐1.01, P = 0.064)." (PMID 31341530, 2019). "However, no publications have reported the associations of APEX1 gene polymorphisms with neuroblastoma risk." (PMID 31341530, 2019). "Given the potential effects of APEX1 polymorphisms on the ability of the DNA damage repair, many studies have investigated the association between these variants and susceptibility to several types of cancer but not neuroblastoma." (PMID 31341530, 2019).
pancreatic ductal adenocarcinoma (4 papers, 2017 to 2023). An infiltrating adenocarcinoma that arises from the epithelial cells of the pancreas. "This is in contrast with the alteration of pathways by APEX1 KD in human cancer lines, such as pancreatic ductal adenocarcinoma, lung, HeLa, and malignant peripheral nerve sheath tumors." (PMID 36674619, 2023).
Parkinson disease (4 papers, 2014 to 2023). A progressive degenerative disorder of the central nervous system characterized by loss of dopamine producing neurons in the substantia nigra and the presence of Lewy bodies in the substantia nigra and locus coeruleus. "Additional drug-gene interactions were observed for APEX1 (Apurinic/Apyrimidinic Endodeoxyribonuclease 1) and N04 drug classification, which comprises of anti-Parkinson drugs, and includes anticholinergic and dopaminergic agents." (PMID 36959830, 2023). "have demonstrated that APEX1 overexpression inhibits the increase of ROS induced by Parkinson’s disease model." (PMID 35311089, 2022).
Sepsis (4 papers, 2016 to 2025). Sepsis is defined as life-threatening organ dysfunction caused by a dysregulated host response to infection. "Violin plots depict the differential expression of CTSD, SLC40A1, PIK3CB (upregulated), and APEX1 (downregulated) in sepsis patients compared to the control group (***p < 0.001)." (PMID 41041634, 2025). "A nomogram was constructed based on the expression profiles of APEX1, CTSD, SLC40A1, and PIK3CB, allowing for individualized prediction of sepsis risk." (PMID 41041634, 2025). "Machine learning-based feature selection identified four robust biomarkers (APEX1, CTSD, SLC40A1, PIK3CB) associated with sepsis." (PMID 41041634, 2025). "Molecular docking analysis further indicated potential interactions between α-HB and key targets (APEX1, CTSD, SLC40A1, PIK3CB), providing insights into the molecular mechanisms of α-HB in sepsis." (PMID 41041634, 2025). "Notably, APEX1, CTSD, SLC40A1, and PIK3CB were consistently selected by all three algorithms, underscoring their potential as robust marker genes for sepsis diagnosis and progression." (PMID 41041634, 2025).
squamous cell carcinoma (4 papers, 2010 to 2021). A carcinoma arising from squamous epithelial cells. "In summary, the SLC2A1 -2841A>T polymorphism was associated with FDG-uptake in combination with the APEX1 TT genotype in patients with squamous cell carcinoma." (PMID 20540786, 2010). "We analyzed subgroups according to the combinations of SLC2A1, VEGFA, APEX1, and HIF1A polymorphisms in patients with squamous cell carcinomas." (PMID 20540786, 2010).